TNF (tumor necrosis factor)
Diseases named in the same sentence as TNF in open-access papers (continued):
Sharing a sentence is not in itself a finding about the gene and the disease.
chorioamnionitis (continued). "TNF-α further activates the p38-MAPK pathway of neutrophils to promote the aggregation of neutrophils, which increases the risk of chorioamnionitis." (PMID 33765949, 2021). "The optimum cut-off values for the prediction of chorioamnionitis were found to be 1389.82 pg/mL for IL-6, 21.17 pg/mL for TNF-α, and 172.53 ng/mL for MMP-8." (PMID 33800521, 2021). "The MMP-8 and TNF-α analyses can improve the prediction of chorioamnionitis, which is a contraindication to the expectant management and can lead to expedited delivery." (PMID 33800521, 2021). "Several characteristic features of human chorioamnionitis are recapitulated in these models, including neutrophilic infiltration in the placental membranes and elevated IL-1β and TNFα in the amniotic fluid." (PMID 32636848, 2020). "Lastly, it is known that IL-6 and TNF-alpha are increased in chorioamnionitis and these cytokines also result in methylation at the Foxp3 promoter, that then down regulates Treg cell development." (PMID 30473713, 2018). "In the amniotic fluid, levels of IL-1β, IL-6, IL-8, TNFα, CCL3, 4, and 5 are elevated in women with threatened PTL, especially in the presence of intra-amniotic infection, as are IL-1β, IL-6, IL-8, TNFα, and CCL2 in the cervical fluid." (PMID 25741339, 2015). "We previously reported that chorioamnionitis induces a time-dependent increase in the ability of preterm fetal lung and blood monocytes to respond to LPS and TNFα." (PMID 23691033, 2013). "Disease outcome was assessed by microbial culture, in situ detection of U. parvum in fetal and utero-placental tissues, grading of chorioamnionitis, and placental gene expression of IL-1α, IL-1β, IL-6, TNF-α, S100A8, and S100A9." (PMID 22952869, 2012). "C57BL/6 infected animals predominantly exhibited mild to moderate chorioamnionitis (P<0.0001), and a significant reduction in placental expression of IL-1α, IL-1β, IL-6, TNF-α, S100A8, and S100A9 compared to sham controls (P<0.02)." (PMID 22952869, 2012). "Elevated concentrations of IL-1β, IL-6, IL-8, and TNF-α are usually found within the amniotic fluid of patients with chorioamnionitis and/or funisitis." (PMID 22952869, 2012). "Chorioamnionitis was only weakly correlated with amniotic fluid IL-6, IL-8 and TNF-α (Spearman's ρ = 0.23, p<0.001, ρ = 0.22, p<0.001, and ρ = 0.17, p = 0.003, respectively)." (PMID 19668329, 2009). "Cases with histological chorioamnionitis also showed a marked increase in the expression of proinflammatory cytokines (IL-1α, TNF-α) and chemokine IL-8." (PMID 17064297, 2006). "In chorioamnionitis, local levels of cytokines such as IL-1, IL-6 and TNF-α are increased." (PMID 33648480, 2021). "We then studied other pro-inflammatory cytokines that are involved in GBS infection and chorioamnionitis, namely IL-18, IL-6 and TNF-α, to evaluate whether they presented the same sexually dichotomous profile." (PMID 31197179, 2019). "TNFα is a key cytokine in the proinflammatory response of the fetal-placental unit under normal and pathological conditions, its concentration has been found elevated in the amniotic fluid of patients with intra-amniotic infection and preterm labor." (PMID 26446923, 2015). "Antenatal exposure to cytokines, interleukin-6 [IL-6], interleukin-8 [IL-8], tumor necrosis factor-alpha [TNF-a], interleukin-1beta [IL-1b], is a risk factor for developing BPD and might predispose the subset of neonates exposed to chorioamnionitis prenatally to the development of BPD." (PMID 39795932, 2024). "In addition to infection-induced chorioamnionitis, sterile inflammation also exists in the fetal membranes in normal parturition with increased expression of pro-inflammatory cytokines including IL-1β and TNF-α." (PMID 39290694, 2024).
chorioamnionitis (continued). "Interestingly, we noted that the MMP‐8 cut‐off for FIRS was similar to that for histologic chorioamnionitis (MMP‐8: 170.76 vs. 172.53 ng/ml, respectively) although the TNF‐α cut‐off was four‐fold higher for FIRS than for histologic chorioamnionitis (TNF‐α: 89.20 vs. 21.17 pg/ml, respectively)." (PMID 36151969, 2023). "In vivo, a “cocktail” of certain stimuli including bacterial LPS, as a primary and early stimulus, as well as pro-inflammatory, airway-cell-produced cytokines like IL-1β and TNF-α as a secondary stimulus, could be responsible for the synthesis of A20 in the lung in the chorioamnionitis model." (PMID 35096271, 2022). "We compared the ability of suPAR to identify FIRS and FIRS with histological chorioamnionitis with that of other inflammatory biomarkers, such as MMP-8, TNF-α, and IL-6." (PMID 38200448, 2024). "However, the focus on elective cesarean delivery did confer the advantage of reducing the variability of the CB plasma cytokines, because higher cord levels of both IL-1 and TNF-α are seen in chorioamnionitis and long, difficult labors may impact tissue IL-6 levels." (PMID 39683596, 2024). "In ROC analysis, suPAR showed similarly good characteristics in diagnosing FIRS with histological chorioamnionitis, whereas MMP-8, TNF-α and IL-6 performed better in identifying FIRS alone." (PMID 38200448, 2024). "An elevated level of cytokines IL-1β, IL-6, TNFα, IFNγ, EGF, MIP3α in patients with PROM and intra-amniotic infection." (PMID 34745106, 2021). "Our findings, as well as those presented in previous reports, support the use of IL-6, TNF-α, and MMP-8 analyses for the identification of chorioamnionitis in patients presenting with PPROM." (PMID 33800521, 2021). "During chorioamnionitis, the concentration of inflammatory mediators including IL-1β, IL-6, IL-8, MMP9 and TNFα in the amniotic fluid increases dramatically." (PMID 32636848, 2020). "Similarly, in the chorioamnionitis-induced PTB rat model, LPS administration increased cerebral expression of inflammatory and apoptotic markers, such as IL-1β, TNF-α, RANK, and caspase-8." (PMID 41009000, 2025). "TNF-α inhibitors could reverse the increased level of CD63 on neutrophils, suggesting that TNF-α could regulate degranulation of neutrophils during chorioamnionitis." (PMID 37475854, 2023). "Unexpectedly, we did not establish any EGF association with histological chorioamnionitis, FIRS, or inflammatory cytokines such as IL-6, TNF-α, and MMP-8." (PMID 35328399, 2022). "In this study, we found that women with chorioamnionitis had higher vaginal fluid IL-6 and TNF-α concentrations compared to women without this infection." (PMID 33800521, 2021). "The strength of this study is that this is one of the largest reported studies that has sought to determine the cut-off levels for IL-6 and TNF-α, and it is the first study to determine a cut-off level for MMP-8 in vaginally obtained amniotic fluid for the prediction of chorioamnionitis." (PMID 33800521, 2021). "Although amniotic fluid ILC3s produce IL-17A and TNFα, indicating their functionality, their numbers in patients with intra-amniotic infection/inflammation remain unchanged compared to those without this pregnancy complication." (PMID 30416502, 2018). "There is evidence that TNFα is powerful enough to potentiate other inflammatory modulators and to induce preterm labor, fetal injury, and histological chorioamnionitis in a nonhuman primate model." (PMID 26446923, 2015). "Conversely, severe protracted chorioamnionitis with cellular necrosis was the predominant lesion phenotype in BALB/c mice, which also exhibited a significant increase in placental expression of IL-1α, IL-1β, IL-6, TNF-α, S100A8, and S100A9 (P<0.01)." (PMID 22952869, 2012). "On the other hand, TNFα, whose negative effects on the course of pregnancy have been characterized, increases in the amniotic fluid of women with preterm labor and intra-amniotic infection." (PMID 18078521, 2007).
chorioamnionitis (continued). "However, corresponding elevated maternal plasma markers of inflammation (IL-1β, IL-2, IL-6, IFN-γ and TNF-α) have not been shown to be accurate for the diagnosis of chorioamnionitis." (PMID 40464837, 2025). "Thus, in our chorioamnionitis model, A20 may regulate TLR-induced airway inflammation accompanied by a reduction of IL-1β, IL-6, IL-8, and TNF-α." (PMID 35096271, 2022). "Furthermore, the cord blood levels of IL-8, TNF-α, and granulocyte colony-stimulating factor (G-CSF) were significantly higher in chorioamnionitis patients with FIR than those without FIR." (PMID 35453930, 2022). "Intra-amniotic injections in fetal sheep of IL-1 or E. coli endotoxin lipopolysaccharides (LPS), but not IL-6, IL-8, or TNF-α, induce chorioamnionitis and early lung maturation as measured by large increases in pressure–volume curves and lung mechanics and gas exchange within 5 to 7d." (PMID 26301222, 2015). "Although a clinical study suggested that TNF-α level was not significantly different in cord blood between pregnancies with and without clinical chorioamnionitis, our result was different, and this difference may be due to discrepant clinical and HCA diagnostic criteria." (PMID 33765949, 2021). "However, all the samples were obtained using the same technique, and the values of IL-6, TNF-α, and MMP-8 were statistically higher in the chorioamnionitis group than in the noninfection group." (PMID 33800521, 2021).
pertussis (57 papers, 2011 to 2025). A contagious bacterial respiratory infection caused by Bordetella pertussis. "The minor allele of the TNFα SNP (c.308G>A; rs1800629) was present at a higher frequency in the pertussis patient group (19.8%) compared to the control population group (16.7%), however the difference was not significant." (PMID 26894582, 2016). "KEGG pathway analysis further revealed significant enrichment in canonical inflammatory cascades, including TNF, Toll-like receptor, and NF-κB signaling, alongside terms linked to coronavirus disease and pertussis, which likely reflect shared innate immune and host-pathogen response modules." (PMID 41488001, 2025). "What's more there were markedly enriched in TNF signaling pathway (p < .01), pertussis (p < .01), and complement and coagulation cascades (p < .01) in KEGG pathway." (PMID 36988255, 2023). "Previous studies have also demonstrated that the pertussis vaccine was immunogenic and safe in pediatric patients with UC, particularly when used in combination with anti-TNF-α agents." (PMID 33144895, 2020). "Single-nucleotide polymorphisms (SNPs) in candidate genes, MBL2, IL17A, TNFα, VDR, and IL10 were genotyped in a unique Dutch cohort of symptomatic clinically confirmed (ex-)pertussis patients and in a Dutch population cohort." (PMID 26894582, 2016). "Allele frequencies and OR for the VDR, TNFα, IL17, MBL2 and IL10 SNPs in the pertussis patient group and control group." (PMID 26894582, 2016). "Notably, in both groups of children, CD3+CD4+ effector memory cells producing simultaneously IFN-γ and TNF-α upon stimulation with pertussis antigens were found, indicating that one cell is able to produce more than 1 cytokine." (PMID 22860033, 2012). "Regarding cellular immunity, 15 days after vaccination, frequency of pertussis-specific CD4+ T cells, quantified by staining for IFN-γ, IL-2 and TNF-α, was equivalent in both groups supporting the induction of T cell immunity." (PMID 37468500, 2023). "Suppression of the TNF signaling pathway was also observed in cells infected by SARS-CoV-2, along with simultaneous activation of complement and coagulation cascades and pertussis pathways." (PMID 38681774, 2023). "For the Pertussis pathway, the main responsible genes for the pathways were CASP3, IL-1β, IL-1, IL-6, TNFα, and iNOS." (PMID 37895148, 2023). "The most recent findings have demonstrated the protective role that maternally derived cytokines, such as tumor necrosis factor (TNF)-α, IFN-γ, interleukin (IL)-6, IL-8 and IL-12/IL-23p40, play in a pertussis model." (PMID 28763018, 2017). "Genotype frequencies and OR for the VDR, TNFα, IL17, MBL2 and IL10 SNPs in the pertussis patient group and control group." (PMID 26894582, 2016). "Furthermore, pathways mostly affected by these genes included cytokine-cytokine receptor interaction, influenza A, Pertussis, NOD-like receptor, TNF, NF-kappa B, and IL-17 signaling pathways." (PMID 39051372, 2024). "In the PT2 infants, central memory CD8T cells (CD300a MFI) increased 2.2 fold with pertussis and 1.02-fold, increased, central memory CD8 T cells (TNF-α MFI) and BCMA+ plasma cells raised 1.5-fold with HBsAg while central memory CD8 T cells (CD300a MFI) increased 2.33 fold for HiB." (PMID 33968011, 2021). "Pertussis antigens contained in the Tdap-IPV vaccine have been previously shown to induce cytokine production in vitro; FHA induces TNF-α production in human monocyte-derived macrophages and stimulates the production of IL-10 and IL-6 in mouse macrophages and DCs." (PMID 34649076, 2021). "Multiple logistic regression demonstrated that female sex and methotrexate use, but not TNF inhibiting medications, correlated with reduced immunity to pertussis." (PMID 31136605, 2019).
pertussis (continued). "Other authors have demonstrated that a transgenic mouse that expressed CCL2 under the GFAP promoter developed pertussis-induced reversible inflammatory encephalopathy and that CCL2 directed a Th1-biased inflammatory reaction, as shown by high levels of TNF-α, INFγ and IL-2 in the CNS." (PMID 23866683, 2013). "Interestingly, despite the high level of immune suppression attributed to TNF inhibiting medications, we did not see a correlation between TNF inhibitor use and reduced pertussis immunity or lower pertussis titers." (PMID 31136605, 2019).
silicosis (57 papers, 2009 to 2025). Silicosis is a respiratory disease caused by breathing in (inhaling) silica dust. "Studies showed that TNF-α levels are elevated before the onset of clinical signs associated with silicosis, making TNF-α a valuable option for early diagnosis." (PMID 36672608, 2022). "Alongside TNF, results showed that IL-1 polymorphisms genotyping, especially IL-1RA +2018, can be related to the susceptibility and severity of silicosis." (PMID 36672608, 2022). "A meta-analysis assigns that TNF -308 (11 studies) and -238 (8 studies) polymorphisms are associated with susceptibility of silicosis." (PMID 36672608, 2022). "Chronic silicosis is caused by inflammatory mediators such as interleukins, tumor necrosis factor (TNF)-α, transforming growth factor (TGF)-β, and reactive oxygen species (ROS)/reactive nitrogen species (RNS)." (PMID 33671768, 2021). "In summary, this updated meta-analysis suggests that TNF −308A/G and −238A/G polymorphisms are associated with susceptibility to silicosis." (PMID 30643011, 2019). "A significant association of AA+AG genotype of the TNF −308 A/G polymorphism with susceptibility to silicosis was also found (OR = 1.466, 95%CI = 1.226–1.753, P<0.001)." (PMID 30643011, 2019). "On the other hand, several studies discussed association of TNF gene polymorphisms in patients with silicosis, but results were inconsistent." (PMID 30643011, 2019). "More studies concerning the association between TNF polymorphisms and silicosis risk have been reported in recent years." (PMID 30643011, 2019). "The meta-analysis suggests that the TNF −308A/G and −238A/G polymorphisms are associated with susceptibility to silicosis, especially in Asians." (PMID 30643011, 2019). "Eight case–control studies including 1191 cases and 1101 controls identified an association between the TNF −238A/G polymorphism and silicosis risk." (PMID 30643011, 2019). "Overall, meta-analysis revealed a significant association between the TNF −308A allele and silicosis (OR = 1.348, 95%CI = 1.156–1.570, P<0.001)." (PMID 30643011, 2019). "The aim of this meta-analysis was to assess association between TNF gene polymorphisms and silicosis susceptibility." (PMID 30643011, 2019). "In a study with Chinese workers exposed to silica particles, there was significant correlation between polymorphisms of TNF −308A/G and −238A/G polymorphisms and risk of silicosis." (PMID 30643011, 2019). "There are already population-based studies on the association between silicosis risks and TNF-α gene polymorphism (308G/A, rs1800629) have been carried out." (PMID 24124578, 2013). "It is verified that the OR of disease for carriers of the minor variant, TNF-α, is markedly higher for severe silicosis and significantly lower for moderate silicosis." (PMID 24124578, 2013). "The present meta-analysis of nine studies provides more comprehensive analysis on the relationship between TNF-α-308A/G gene polymorphism and susceptibility to silicosis." (PMID 24124578, 2013). "Cytokine polymorphisms of TNF-α were found to be associated with the silicosis risk in the Chinese workers exposed to silica particles." (PMID 24124578, 2013). "A meta-analysis was performed in order to drive a more precise estimation of the relationship between TNF-α-308 G/A gene polymorphism and susceptibility to silicosis." (PMID 24124578, 2013). "Tumor necrosis factor-α (TNF-α) 308 G/A gene polymorphism has been reported to be associated with susceptibility to silicosis." (PMID 24124578, 2013). "Despite those limitations, this systematic review of the association of TNF-α-308G/A gene polymorphism with silicosis risk is statistically more convincing than any single study." (PMID 24124578, 2013). "The power analysis shows that our study has a power greater than 80% to detect the effects of TNF-α polymorphism on silicosis susceptibility, assuming an OR of 1.45.Then subgroup analysis was performed to analysis the potential ethnic differences." (PMID 24124578, 2013).